FCN3 (ficolin 3)
Diseases named in the same sentence as FCN3 in open-access papers (continued):
Sharing a sentence is not in itself a finding about the gene and the disease.
tumor (25 papers, 2013 to 2026). "And high FCN3 expression in tumor tissue was independently associated with better overall survival (p = 0.042)." (PMID 38683466, 2025). "A high FCN3 expression in tumor tissue was independently associated with better overall survival (p=0.042)." (PMID 37484802, 2023). "Among the DEGs down-regulated in tumor tissues, which represent potential tumor suppressors, was FCN3, a gene encoding a lectin protein proposed to be involved in innate immunity." (PMID 33859174, 2021). "Indeed, for the 58 TCGA LUAD cohorts, higher expression levels of FCN3 were strongly associated with better survival consistent with a meaningful role of FCN3 as a tumor suppressor gene." (PMID 33859174, 2021). "This work revealed the dual role of FCN3 as both a tumor suppressor and immunomodulator, whose function was modulated by N-glycosylation at Asn189." (PMID 41493695, 2026). "Of note, WB analysis in clinical samples showed not only decreased FCN3 expression but also the presence of a higher molecular weight band in tumor tissues, indicative of glycosylated FCN3." (PMID 41493695, 2026). "Clinical sample analysis revealed markedly reduced FCN3 expression in HCC tumor tissues compared to adjacent non-tumor tissues." (PMID 41493695, 2026). "Ficolin-3 (FCN3) is a crucial immunomodulatory molecule that regulates immune escape by remodeling the tumor microenvironment." (PMID 40114488, 2025). "PPI network analysis implicated CCBE1 and FCN3 as candidates for interaction with COLEC10, with their reduced expressions in tumor tissues and significant correlation with patient survival." (PMID 40026364, 2025). "To explore the clinical significance of FCN3 in HCC, we examined FCN3 expression in 134 tumor specimens from an HCC tissue microarray with FCN3 antibody staining." (PMID 38698462, 2024). "Whereas, to be tumor suppressors, ficolin 3 (FCN3), cytochrome P450 family 2 subfamily C member 8 (CYP2C8), and fructose-1,6-biphosphatase (FBP1) have been reported to be downregulated in HCC and inhibited the progression of HCC." (PMID 38664521, 2024). "We next investigated the clinicopathological variables of the patients according to FCN3 expression levels in the tumor tissue specimens." (PMID 37484802, 2023). "In this study, we assessed the prognostic role of FCN3 for HCC using survival analysis based on the FCN3 expression in tumor tissues, and found that the patients with a low FCN3 expression had significantly worse overall survival in univariate analysis." (PMID 37484802, 2023). "The proportion of EdU positive cells in tumor tissues was confirmed, and a significant decrease in the FCN3 group was observed compared to the control group." (PMID 36632465, 2023). "We discovered that FCN3 overexpression significantly reduced the volume of subcutaneous xenograft tumors and restrained tumor growth." (PMID 36632465, 2023). "Our findings of significantly better overall survival in the patients with a high expression of FCN3 in tumor tissues are consistent with previous studies 7,17,19-21." (PMID 37484802, 2023). "Rather, the ER stress induced by intra-ER FCN3 appears to account for its role as a tumor suppressor." (PMID 33859174, 2021). "We show that tumor suppressor activity of FCN3 is based on induction of ER stress response which can result in cell death under certain circumstances." (PMID 33859174, 2021). "Taken together, these results strongly suggest that tumor suppressor activity of FCN3 is cell-autonomous and mediated by an intracellular mechanism." (PMID 33859174, 2021). "We also examined the expression pattern of FCN3 in other tumors with a sufficient number of matched normal and tumor tissues." (PMID 33859174, 2021). "Collectively, our data indicate that FCN3 is a tumor suppressor gene functioning through induction of ER stress." (PMID 33859174, 2021). "FCN3 showed a consistency >95% (i.e. 97 out of 102 patients showed down-regulation in tumor tissues) and the average Log2 fold change of 3.72." (PMID 33859174, 2021).
tumor (continued). "To further understand ER stress-mediated by FCN3, we generated several FCN3 derivatives and tested their tumor suppressor activity using colony formation assay and flow cytometry for apoptosis." (PMID 33859174, 2021). "In order to dissect the molecular nature of the tumor suppressor activity, we carried out transcriptome sequencing for FCN3-expressing A549 cells and control samples in duplicates." (PMID 33859174, 2021). "Correlation analysis in clinical tumor tissues further showed that STT3A protein levels were inversely associated with total FCN3 expression, suggesting a link between STT3A expression and FCN3 regulation." (PMID 41493695, 2026). "Particularly noteworthy was the observation that N-glycosylation disrupted the tumor-suppressive function of FCN3, suggesting that HCC cells might actively exploit this post-translational modification to create an immunosuppressive microenvironment." (PMID 41493695, 2026). "However, the glycosyltransferase STT3A mediated N-glycosylation of FCN3 at Asn189, thereby disrupting the tumor-suppressive function of FCN3 in HCC." (PMID 41493695, 2026). "In addition, among 33 pairs of HCC and non-tumor tissues, FCN3 expression levels showed a consistency strong immunostaining (3+ to 4+) in non-tumor tissues." (PMID 37484802, 2023). "FCN3 has been shown to be epigenetically silenced in various tumors 7,10,17, 19,20, suggesting that abnormally expressed FCN3 may participate in activation of the lectin complement pathway during tumor development." (PMID 37484802, 2023). "However, further studies are needed to investigate the association between the expression patterns of FCN3 in HCC tissues and tumor progression." (PMID 37484802, 2023). "Besides, FCN3 overexpression linked with both favorable OS (HR = 0.58, P = 0.037) and PFS (HR = 0.64, P = 0.048) of patients with Grade 2 tumor." (PMID 33878734, 2021). "We also examined the tumor suppressor activity of FCN3 using a xenograft model." (PMID 33859174, 2021). "Here, we present data for the first time indicating that FCN3 is a tumor suppressor gene of LUAD." (PMID 33859174, 2021). "Actually, we conceived the same idea as den Brok that tumour antigens released by tumours in situ or in the serum might induce an antitumour immune response, leading to a better prognosis, and Ficolin-3 might be one of those antigens." (PMID 29386009, 2018). "Therefore, N‐glycosylation of FCN3 may not only impair its function but also reduce its intracellular retention, thereby attenuating its tumor‐suppressive activity." (PMID 41493695, 2026). "By analyzing the correlation of FCNs expression with tumor mutation burden and microsatellite instability in 33 type of human tumors, FCN1 expression was found to be significantly correlated with MSI of HCC (p < 0.05); FCN3 expression was significantly correlated with TMB and MSI of HCC (p < 0.05)." (PMID 35928441, 2022). "FCN3 and age, tumor stage, T, and N were all correlated, but not with T, of which T (P = 6.401E-04) was most significantly correlated with FCN3, suggesting that FCN3 might play an important role in the size and the metastasis of primary tumor." (PMID 33195408, 2020). "In contrast, FCN3 and OIT3 were commonly downregulated, both known for their tumor-suppressive and immune-regulatory functions, highlighting their potential as universal biomarkers or therapeutic targets." (PMID 41216224, 2025). "Further examination indicated that lower FCN3 expression was significantly correlated with higher alpha-fetoprotein (AFP) level, larger tumor size, higher TNM stage, and earlier recurrence." (PMID 38698462, 2024). "Clinical data analysis indicated that low expression of FCN3 was significantly correlated with AFP, tumor size, number of tumors, microvascular invasion and Edmondson-Steiner classification in 202 patients of HCC." (PMID 36632465, 2023). "We identified three critical genes (FCN3, CDC20, and E2F1) involved tumor prognosis in HCC patients." (PMID 35402624, 2022).
tumor (continued). "Formation of colony was dramatically inhibited upon expression of FCN3 in a similar manner to that of CDKN2A, a well-established tumor suppressor gene." (PMID 33859174, 2021). "Additionally, although we found that Ficolin-3 might be used as a tumour vaccine for the prevention and therapy of residual tumour through stimulation of the immune system, we have not proven this hypothesis, which we hope to confirm in a future animal study or even with preclinical tests." (PMID 29386009, 2018). "Multivariate analysis showed that age ≥65 years and poor differentiation but not sex, hepatitis B/C virus (HBV/HCV) infections, tumor size, stage, and FCN3 expression were independent prognostic indicators in the HCC patients." (PMID 37484802, 2023). "We further examined the transcriptional level of FCN3 in paired tumor vs non-tumor samples by qRT-PCR." (PMID 36632465, 2023). "This suggested that there may be lower levels of FCN3 in HCC tissues, and that FCN3 may be a tumor suppressor." (PMID 37484802, 2023). "Of interest, FCN3 does not appear to be a universal tumor suppressor in that aside from LUAD we saw statistically significant down-regulation only in BRCA, KIRP, LIHC, and LUSC." (PMID 33859174, 2021). "We found that Ficolin-3 was overexpressed in the serum of most HCC patients after RFA and might be a potential biomarker for RFA treatment efficacy and tumour vaccine development for HCC immunotherapy." (PMID 29386009, 2018). "FCN3+ endothelial cells and ACTA2+ fibroblasts are significantly lost when the phenotype becomes metastatic, indicating that the blood vessels may be broken and the formation of tumor thrombus is promoted." (PMID 38824541, 2024). "However, the expression pattern of FCN3 in HCC tissues and its contribution to tumor progression remains unclear." (PMID 36632465, 2023). "The sub‐clustering of ECs revealed six subtypes, including extra‐alveolar capillary EC (cEC) (FCN3+EDN1+PLVAP+), alveolar cEC (HPGD+EDNRB+IL1RL1+), arterial EC(GJA5+FBLN5+DKK2), lymphatic EC (CCL21+TFF3+FABP4), INSR+ tumour EC (INSRhiHSPG2+PLVAP+), and ACKR1+ tumour EC (ACKR1+SELP+IL1R1+)." (PMID 35184398, 2022). "However, estimation of the expression of either FCN2 or FCN3 gene does not distinguish between patients with less or more advanced disease stage, particular histological types or tumour grade, at least with the relatively small number of samples investigated here." (PMID 23744477, 2013). "Expression levels of FCN3 and CCBE1 were found to be significantly reduced in tumor tissues compared to their non-tumor matched normal counterparts from the GTEx database (Figure 2Gb and Hb)." (PMID 40026364, 2025). "We further assessed FCN3 expression across 15 discrete groups, comprising HCC tumor specimens (T), their corresponding adjacent non-tumor tissues (N), and portal vein tumor thrombus (P, PVTT)." (PMID 38698462, 2024).
infection (8 papers, 2016 to 2022). The state of being infected such as from the introduction of a foreign agent such as serum, vaccine, antigenic substance or organism. "Thus, FCN3 A allele carrying patients may be at high risk for recurrent infection, and a higher likelihood to develop RHD." (PMID 33499929, 2021). "Results: hA-MSCs added to AF significantly reduce the proliferation of both bacterial strains at 24 h and diversely affect M1 and M2 polarization, C3a complement protein, and ficolin 3 concentrations during the course of infection, in a bacterial strain-dependent fashion." (PMID 35055040, 2022).
bacterial infections (4 papers, 2013 to 2024). "Activity of ficolin-3-mediated lectin pathway (F3-LP) in relation to anatomic location of bacterial infections." (PMID 30949171, 2019). "In summary, we found impaired ficolin-3-mediated lectin pathway activation and decreased alternative pathway amplification during bacterial infections in patients with T2DM in comparison with non-diabetic individuals." (PMID 30949171, 2019).
renal disease (1 paper, 2016). "As anti-ficolin-3, anti-C1q, anti-dsDNA and low complement C3 and/or C4 were associated with renal disease activity, we characterized the diagnostic performances of these biomarkers, alone or in combination, in our cohort." (PMID 27631981, 2016).
FCN3 also shares sentences with these, for which no sentence is quoted: rheumatic fever (3 papers); acute leukemia (2); atherosclerosis (2); cardiovascular disease (2); colorectal cancer (2); coronary heart disease (2); diabetic kidney disease (2); multiple myeloma (2); tuberculosis (2); adenoma (1); aneurysm (1); attention deficit-hyperactivity disorder (1); Berger disease (1); breast invasive carcinoma (1); diabetic retinopathy (1); dilated cardiomyopathy (1); head and neck cancer (1); hepatitis B (1); hepatoblastoma (1); infarct (1); infectious disease (1); kidney damage (1); liver dysfunction (1); liver fibrosis (1); malaria (1); metabolic disease (1); microcephaly (1); pneumonia (1); postherpetic neuralgia (1); prediabetes (1).
A further 6 diseases each share a sentence with FCN3 in 1 paper.